MACC1 (MET transcriptional regulator MACC1)
Diseases named in the same sentence as MACC1 in open-access papers (continued):
Sharing a sentence is not in itself a finding about the gene and the disease.
colorectal cancer (continued). "A tumor suppressor miRNA, miR-218, posttranscriptionally suppressed the MACC1 expression and its metastasis-promoting abilities in colorectal cancer." (PMID 31039730, 2019). "Herein, our data revealed that plasma MACC1 levels in 117 colorectal cancer patients (CRC) were dramatically higher than that in normal controls (P < 0.001), and with a strong discrimination power between the two groups (AUC = 0.960, P < 0.001)." (PMID 30370603, 2019). "MSI2, MACC1 and TAGLN were reported to be associated with ovarian cancer, colorectal cancer and esophageal cancer, respectively." (PMID 31640538, 2019). "In colorectal cancer, miR-218 has been shown to target metastasis related gene MACC1 and inhibit cancer progression." (PMID 29977158, 2018). "Meanwhile, in colorectal cancer, miR-218 is proved to target pro-tumorigenesis gene MACC1 and BMI-1 to inhibit CRC development." (PMID 29977158, 2018). "In the meantime, loss of TTP increased the growth rate and migration capability of colorectal cancer cells due to the upregulation of ZEB1, sex-determining region Y box 9 (SOX9), and metastasis-associated in colon cancer 1 (MACC1)." (PMID 30380668, 2018). "MACC1 was first described as a key driver of metastasis formation in colorectal cancer, and its importance was later confirmed for other solid tumor entities." (PMID 28570591, 2017). "By geographic protein expression analysis, we illustrate that MACC1 is differentially expressed in normal mucosa, tumor center and at the invasive front of colorectal cancer." (PMID 25884643, 2015). "It was partly elucidated that hsa-miR-574-5p played a suppressive role in colorectal cancer liver metastasis by negatively directing MACC-1 expression, offering a novel therapeutic approach for colorectal cancer liver metastasis." (PMID 24936152, 2014). "Based on the evidence that c-MET is a target gene of MACC1 in colorectal cancer, the c-MET promoter fragments between −223 and +60 were amplified and cloned into a pGL3-basic vector, which is a positive regulatory element." (PMID 25009663, 2014). "Subsequently, results demonstrated that hsa-miR-574-5p was involved in the regulation of MACC-1, playing a functional role in colorectal cancer liver metastasis." (PMID 24936152, 2014). "Increased MACC-1 expression in colorectal cancer cells can induce proliferation, migration and invasion of cancer cells in vitro, while promoting liver metastasis in a xenograft model." (PMID 24936152, 2014). "Taken together, our findings partly elucidated that hsa-miR-574-5p played a suppressive role in colorectal cancer liver metastasis by negatively directing the expression of MACC-1." (PMID 24936152, 2014). "Our work firstly demonstrated that hsa-miR-574-5p negatively regulated MACC-1 expression in colorectal cancer cells." (PMID 24936152, 2014). "For the first time, we describe a non-invasive assay for quantification of circulating MACC1 transcripts in blood of more than 300 colorectal cancer patients." (PMID 23166620, 2012). "The metastasis-inducing gene MACC1 is a newly identified gene and its expression is a prognostic indicator for colorectal cancer metastasis." (PMID 22838389, 2012). "Subsequently, several groups validated the link of high MACC1 expression in colorectal cancer tissue to advanced disease." (PMID 23166620, 2012). "To determine the basal levels of circulating MACC1 transcripts in tumor-free volunteers and colorectal cancer patients, we subsequently separated plasma from 4°C-cooled blood samples within the first 7 hours after blood taking." (PMID 23166620, 2012). "Several groups confirmed meanwhile a correlation of high MACC1 expression in the tumor to progression, metastasis, survival, and therapy response in colorectal cancer (CRC)." (PMID 23166620, 2012). "Previous studies have shown a positive correlation between CCN1 and MACC1 in colorectal cancer." (PMID 38396744, 2024).
colorectal cancer (continued). "There are reports that IFN-γ can promote the metastasis of colorectal cancer through MACC1, so IFN-γ may promote the metastasis of LCA through some yet undefined mechanism." (PMID 38903721, 2024). "Curcumin reduces MACC1 expression and inhibits wound healing in colorectal cancer." (PMID 39062099, 2024). "MACC1 has been demonstrated to play an important role in metastasis formation in colorectal cancer." (PMID 39062099, 2024). "Interestingly, both TNFα and NFκB expression are upregulating MACC1 expression in colorectal cancer cells." (PMID 37627117, 2023). "The molecular mechanism of Macc1 has been extensively investigated in colorectal cancer." (PMID 37841442, 2023). "MACC1 knockdown was also found to markedly inhibit cell proliferation, migration, invasion, colony formation, and tumorigenesis, both in vitro and in vivo, and to induce apoptosis in colorectal cancer (CRC) cells." (PMID 36545127, 2022). "There are many reports show that MACC1 is a predictor of the prognosis of colorectal cancer." (PMID 34343214, 2021). "However, FOXA3 was demonstrated to repress stemness of colorectal cancer cells via targeting MACC1, whose gene expression is enriched in neural cells during early embryogenesis." (PMID 34595169, 2021). "We aimed at the systematic identification of MACC1-driven metabolic networks in colorectal cancer." (PMID 33652667, 2021). "Initially, expression of SPON2 by MACC1 regulation was reported to promote colorectal cancer." (PMID 32492954, 2020). "In colorectal cancer, miR-143 inhibited cell migration and invasion by targeting MACC1." (PMID 31039730, 2019). "Importantly, expressions of MACC1 and DBC1 are positively correlated with each other, upregulated in high-risk groups of colorectal cancer patients, and associated with poor survival." (PMID 30082743, 2018). "Others cancers, such as lung and colorectal cancers, exhibit high MACC1 serum levels and may thus impair accurate BC diagnosis." (PMID 27793048, 2016). "However, the prognostic and clinicopathological value of MACC1 in colorectal cancer remains inconclusive." (PMID 27542234, 2016). "MACC1 is considered an independent factor for prognosis and metastasis in colorectal cancer." (PMID 27832750, 2016). "MACC1 expression level can serve as a novel prognostic factor in colorectal cancer patients." (PMID 27542234, 2016). "Subsequent clinical investigations showed that MACC1 might be useful in the prognostic classification of colorectal cancer patients and was a promising new target for intervention in metastasis." (PMID 27542234, 2016). "Therefore, we conducted this meta-analysis to investigate the effect of MACC1 overexpression on clinicopathological features and survival outcomes in colorectal cancer." (PMID 27542234, 2016). "Therefore, it is necessary to investigate the effects and molecular mechanisms of MACC-1 and its upstream regulatory miRNAs to modulate colorectal cancer liver metastasis." (PMID 24936152, 2014). "Previous research also showed that MACC-1 protein in colorectal cancer could bind to c-met promoter through nuclear translocation to up-regulate c-met gene transcription and expression." (PMID 24936152, 2014). "In addition, examination of the MACC1 transcript level in the blood samples collected from colorectal cancer patients has revealed an abnormal increase of MACC1 transcripts with the highest MACC1 transcript levels identified in individuals with metastases." (PMID 24949951, 2014). "Here we confirmed that metastasis-associated in colon cancer 1 (MACC1) and β-catenin expression were higher in colorectal cancer (CRC) cells and tissues than those in normal colonic epithelial cell line and adjacent non-tumour colorectal mucosa (ANM) tissues, respectively." (PMID 25003996, 2014). "MACC1 is a newly identified key regulator of HGF-MET signaling in colorectal carcinoma." (PMID 23573286, 2013).
colorectal cancer (continued). "We had chosen these metastasis biomarkers for combination, since they address most relevant signaling pathways in colorectal cancer progression and metastasis: MACC1 - a key regulator of the HGF/Met signaling pathway, and S100A4– a transcriptional target gene of the Wnt/β-catenin signaling pathway." (PMID 23166620, 2012). "Furthermore, we performed biological assays in order to evaluate the functional impact of MACC1 SNPs on the motility of colorectal cancer cells." (PMID 22838389, 2012). "Colorectal cancer patients characteristics and circulating MACC1 transcript levels in plasma." (PMID 23166620, 2012). "Furthermore, we studied the functional effect of the identified MACC1 SNPs on the migratory, proliferative or wound healing potential of colorectal cancer cells by in vitro assays." (PMID 22838389, 2012). "Studies indicate that in human colorectal cancer cells, the proximal flanking region of MACC1 (−426 nt to −18 nt) is the core promoter that harbors functional elements for binding of transcriptional factors and is responsible for basal transcription of MACC1 mRNA." (PMID 37664587, 2023). "MACC1 overexpression could contribute to colorectal cancer progression and metastasis." (PMID 38021160, 2023). "MACC-1 could be targeted by miR-143 to inhibit cell invasion and migration in colorectal cancer." (PMID 24936152, 2014). "Therefore, we speculated that hsa-miR-574-5p played a suppressive role in colorectal cancer liver metastasis by negatively involved in the down-regulation of MACC-1 expression." (PMID 24936152, 2014). "Our new findings of circulating MACC1 transcripts in plasma of colorectal cancer patients for diagnosis and prediction of survival are in line with those that we reported previously based on the quantification of mRNA expression in colorectal cancer tissues with respect to disease prognosis." (PMID 23166620, 2012). "We have previously identified MACC1 and IER2 as functional biomarkers in the context of colorectal cancer." (PMID 41897334, 2026). "Taken together, these findings show a functional interplay between the colorectal biomarkers MACC1 and IER2, which, in turn, has an impact on the survival of colorectal cancer patients." (PMID 41897334, 2026). "MACC1 promotes the development of colorectal cancer by activating the HGF/c-MET signaling pathway, which is consistent with the high expression of MACC1 in our sequencing results." (PMID 40740230, 2025). "Overexpression of MACC1 has been demonstrated to upregulate the HGF-MET signaling pathway, which in turn promotes tumor proliferation, invasion, and metastasis in colorectal cancer." (PMID 38021160, 2023). "The roles of MACC1 in cancer invasion, epithelial-to-mesenchymal transition, HGF-triggered scattering of cancer cells and metastasis have been first identified in colorectal cancer in vitro and in vivo, and subsequently described in other types of cancers." (PMID 37496665, 2023). "Another hint suggesting that MACC1 interacts with cell–cell and cell–matrix adhesions was implied by the interaction of MACC1 with SPON2 in colorectal cancer." (PMID 37051546, 2023). "We employed GIPC1/MACC1-manipulated cell lines for in vitro and in vivo analyses, and we probed the GIPC1/MACC1 impact using human primary colorectal cancer (CRC) tissue." (PMID 38144523, 2023). "Increased MACC1 expression also leads to EGFR and its mediated downstream signaling pathway activation and cell proliferation, promoting the progression of colorectal cancer." (PMID 35242498, 2022). "Also, MACC1 has been reported to facilitate CSCs-like properties of colorectal cancer cells through the (phosphoinositide 3-kinase/protein kinase B) PI3K/AKT pathway, suggesting that MACC1 may be one of the most important components of CSCs networks in colon cancer." (PMID 34939526, 2022). "Evidence revealed that MACC1 can activate the HGF/MET signaling axis and enhance colorectal cancer cell metastasis and recurrence." (PMID 34939526, 2022).
colorectal cancer (continued). "The MACC1-induced biological and phenotypical effects were reduced in vitro and in vivo by using the MEK1-inhibitor selumetinib (AZD6244) in colorectal cancer." (PMID 35406545, 2022). "Based on the previous research, this study added new molecular probes (18F-FLT) and biological indicators (MACC1, SPON2), which are intended to conduct in-depth research on the mechanism of liver metastasis of colorectal cancer, and select new organisms." (PMID 33712897, 2021). "However, the role of MACC1 in the metabolism of colorectal cancer (CRC) is unknown." (PMID 33652667, 2021). "In this paper, MACC1 and SPON2 were introduced to explore its mechanism of action in colorectal cancer metastasis." (PMID 33712897, 2021). "Our results establish MACC1 as a transcriptional target of Wnt/β-catenin signaling and suggest that DBC1 plays a key role in colorectal cancer progression through Wnt/β-catenin-MACC1 signaling axis." (PMID 30082743, 2018). "As an additional technical validation step, we assayed four genes (APC, MACC1, DCC, and DSC2) that have been previously established to be differentially expressed between tumor and adjacent normal tissue in colorectal cancer." (PMID 22363440, 2012). "Two genes, MACC1 and SALL4, were specifically documented for colorectal cancer." (PMID 39484215, 2024). "Another study performed in colorectal cancer found MACC1 to affect collective but not single-cell migration." (PMID 37051546, 2023). "Two colorectal cancer cell lines with different intrinsic S100A4 and MACC1 gene expression levels were used: HCT116 cells with moderate expression levels of S100A4 and MACC1 and SW620 with high expression levels of S100A4 and MACC1." (PMID 36674695, 2023). "We thereby found that MACC1 expression does not affect the migration and biomechanics of single colorectal cancer cells but does affect collective migration dynamics in a proliferation-dependent manner." (PMID 35740524, 2022). "Therefore, based on this study, the new tumor metastasis markers MACC1 and SPON2 were combined to detect the physiological function of liver metastasis of colorectal cancer." (PMID 33712897, 2021). "That is, the uptake characteristics of 18F-FLT and 18F-FMISO tracers can reflect the invasion and metastasis ability of colorectal cancer, and can be detected by MACC1 expression level, which has not been reported in previous studies." (PMID 33712897, 2021). "Moreover, higher glucose levels increased MACC1 mRNA and protein amount in SW620, HCT116, HT29 and HCT15 colorectal cancer cells." (PMID 33652667, 2021). "Other than colorectal cancer (CRC), MACC1 is also considered a biomarker for several other cancers." (PMID 34072650, 2021). "Furthermore, we found that MACC1 acts a key regulator of the HGF (hepatocyte growth factor)/Met-pathway, which is crucial in colorectal cancer for tumor progression and metastasis formation." (PMID 23166620, 2012). "MACC1 is a predictor for colorectal cancer metastasis independent of tumor stage, age, sex, tumor infiltration, nodal status and lymph vessel invasion, and thus allows identification of subjects at high risk for metastasis in early stages." (PMID 23166620, 2012). "However, it is not completely clear which miRNAs are the regulators for MACC-1 which is the key candidate gene for colorectal cancer liver metastasis." (PMID 24936152, 2014). "The occurrence and frequencies of MACC1 SNPs in primary tumors of colorectal cancer patients were unknown but their frequencies in different non-cancer populations can be found in SNP databases." (PMID 22838389, 2012). "Thus, the MACC1 SNPs L31V, S515L, and R804T have no impact on the migratory ability of colorectal cancer cells (P = 0.77, P = 0.12, P = 0.27)." (PMID 22838389, 2012).
colorectal cancer (continued). "The combination of the two metastasis-inducing genes, MACC1 - a key regulator of the HGF/Met signaling pathway, with S100A4– a transcriptional target gene of the Wnt/β-catenin signaling pathway, improves survival prediction for newly diagnosed colorectal cancer patients." (PMID 23166620, 2012). "Thus, a general screening for these MACC1 SNPs in colorectal cancer patients is not recommended." (PMID 22838389, 2012).